UCA1 (urothelial cancer associated 1)
Diseases named in the same sentence as UCA1 in open-access papers (continued):
Sharing a sentence is not in itself a finding about the gene and the disease.
cancer (continued). "Again, high UCA1 expression was detected in exosomes secreted from CAFs, and exosomal UCA1 was transported to cancer cells." (PMID 33050576, 2020). "C/EBPα and Ets-2 are the transcription factors which can regulate the expression of UCA1, and the cancer progression can be promoted by UCA1 overexpression through different pathways, including PI3K, AKT, and mTOR-STAT3 signal pathways." (PMID 33680939, 2020). "Expression levels of GAS8-AS1 and UCA1 in OS tissues were determined by RT-qPCR, and the expression data were compared by paired t test between OS and non-cancer tissues." (PMID 32013985, 2020). "In order to combine previous research results about UCA1 and cancers to arrive at a summary conclusion, a comprehensive study is performed." (PMID 30918102, 2019). "UCA1 can serve as a potential molecular marker for metastasis and prognosis in different types of cancers." (PMID 30918102, 2019). "In the present study, we found that UCA1 is overexpressed in PCa cancer tissues, as well as PCa cells." (PMID 30940776, 2019). "Urothelial cancer associated 1 (UCA1) is a long noncoding RNA having aberrant expression in embryogenesis and a broad range of cancer tissues and cells." (PMID 31040354, 2019). "In cancer tissues, UCA1 is regulated by HIF1-α, indicating its involvement in the response to hypoxia." (PMID 32039022, 2019). "In the present meta-analysis, we systematically explore the relationship between UCA1 and cancer metastasis or prognosis." (PMID 30918102, 2019). "Several studies have demonstrated that UCA1 expression is also upregulated in multiple types of other cancers, which include CRC, LC, BC, HCC, GC, and ESCC." (PMID 31480503, 2019). "In contrast, the overexpression of UCA1 in DU-145 showed increased level of E-cadherin but decreased level of Vimentin, MMP-9 and N-cadherin (P<0.01), validating the aggressive role of UCA1 in cancer metastases." (PMID 30940776, 2019). "Second, UCA1 promoted the progression of different cancer by activating of the Wnt/β-catenin signaling pathway." (PMID 30918102, 2019). "UCA1 is a lncRNA whose expression is found to related to the initiation and progression of many kinds of cancers." (PMID 31272462, 2019). "Another lncRNA, UCA1 (urothelial cancer associated 1), also was upregulated in OSCC and enhanced proliferation and metastasis of OSCC cells, which was similar to consequences of other cancers in lung, stomach and bladder." (PMID 31133028, 2019). "The long non-coding RNA UCA1 is reportedly increased in several human tumors and critical for the cell migration, invasion, or proliferation of several cancer cells." (PMID 31572567, 2019). "Along the lines of similar studies, UCA1 was overexpressed in the DEN cancer model, with a transcription level increase of 650% compared to controls." (PMID 31731549, 2019). "After that, UCA1 was also found to be dysregulated in other types of cancers, and UCA1 had different mechanisms in regulating cancer progression." (PMID 31596734, 2019). "UCA1 is highly expressed in cancer cells and mediates transcriptional regulation on an epigenetic level through the interaction with chromatin modifiers, by direct regulation via chromatin looping and/or by sponging the action of a diversity of miRNAs." (PMID 30441811, 2018). "The existence of this complex RNA-based regulatory signaling, which controls cancer-related pathways, paves the way to innovative therapeutic applications of RNA-based anticancer strategies targeting UCA1." (PMID 30195762, 2018). "Moderately expressed oncogenic lncRNA UCA1 has been studied for different pathways and interactions, resulting in cancer progression." (PMID 30189670, 2018). "Until now, several groups have highlighted the metastasis-modulating effect of UCA1 in various cancers." (PMID 29368602, 2018). "Further study demonstrated that UCA1 triggers Wnt/ β-catenin pathway activation and contributes to cancer metastasis." (PMID 29368602, 2018).
cancer (continued). "UCA1 expression has been shown to stimulate factors of the WNT signaling pathway in diverse cancer cell types." (PMID 30441811, 2018). "The effects UCA1 has on cell cycle progression and on cell proliferation is probably an important aspect of chemoresistance in these cancers." (PMID 30441811, 2018). "Overall, gene clustering analysis of the 29 UCA1-related miRNA targets with mirPath v.3 showed a significant implication in cancer signaling pathways such as TGFβ, mTOR and WNT signaling." (PMID 30441811, 2018). "The following sections focus on the role of UCA1 to integrate research on different cancer cells in order to decipher its putative functions and mechanisms of regulation in CRC cells." (PMID 30441811, 2018). "Although we were only able to show UCA1 expression in CRC TMA, staining in TMA of other cancer groups will be investigated to determine if there is differential expression of UCA1 between cancer types." (PMID 30189670, 2018). "This evidence was obtained in different types of cancer cells, but overall these studies show that UCA1 interferes at different levels with cell cycle regulation." (PMID 30441811, 2018). "For example, two published meta-analyses individually analyzed the possibility of lncRNA HULC or UCA1 as a potential prognostic biomarker in the human cancer." (PMID 29568404, 2018). "The high expression of UCA1 is correlated with a bad cancer prognosis, which is probably related to the induction of chemotherapy drug resistance." (PMID 30441811, 2018). "It remains to be explored if the described regulation of transcript levels in diverse cancer cells also regulates UCA1 in colorectal cells." (PMID 30441811, 2018). "Overexpression of lncRNA UCA1 results in resistance to cancer treatments with tamoxifen, 5-fluorouracil, gemcitabine, cisplatinum, doxorubicin, imatinib, and tyrosine-kinase inhibitors targeting EGFR." (PMID 29967761, 2018). "UCA1 is a potential good broad-spectrum biomarker for cancer diagnosis, prognosis or prediction of therapeutic response." (PMID 30377411, 2018). "UCA1 stimulates cell proliferation, and silencing its expression in cancer cells has been shown to arrest the cell cycle in the G0/G1 phase (in CRC and other cancer cells)." (PMID 30441811, 2018). "The lncRNA urothelial cancer associated 1 (UCA1) upregulated in HCC enhances proliferation and tumorigenesis of carcinoma cells." (PMID 30477236, 2018). "In this carcinoma type, UCA1 acts through a long non-coding RNA-mediated sponge mechanism by directly binding to miR-216b and downregulation miR-216b expression." (PMID 29755696, 2018). "Although UCA1 has been shown to have pivotal functions in an increasing number of cancers, little is known about the expression pattern and exact role of UCA1 in CCA." (PMID 29221199, 2017). "Second, because of different types of cancers, the cutoff value of UCA1 expression was different in each eligible study." (PMID 27713161, 2017). "Lnc-UCA1 plays a positive role in cancer cell glucose metabolism through the cascade of mTOR-STAT3/microRNA143-HK2, and reveal a novel link between lncRNA and the altered glucose metabolism in cancer cells." (PMID 28946875, 2017). "Taken together, lncRNA UCA1 is potentially a good broad spectrum biomarker for cancer diagnosis, prognosis or therapeutic monitoring." (PMID 28969100, 2017). "Consistently, other lncRNAs such as HOTAIR, H19 and UCA1 were also found to predict the shorter OS in cancer patients." (PMID 28410241, 2017). "Numerous studies showed that UCA1 expression was upregulated in numerous types of cancers, including hepatocellular cancer, gastric cancer, colorectal cancer, lung cancer and esophageal squamous cell carcinoma." (PMID 29299179, 2017). "Intensive researches have showed overexpression of UCA1 can promote the progression of proliferation, invasion, migration, metastasis, chemoresistance in a variety of cancers." (PMID 28423704, 2017).
cancer (continued). "Multiple studies have suggested that lncRNAs, including MALAT1, CUDR, H19, HOTAIR and UCA1, are involved in chemotherapy resistance of cancer cells." (PMID 29137407, 2017). "Recently, several groups have presented evidence that UCA1 functions as a competing endogenous RNA in cancer cells." (PMID 28327194, 2017). "Several lncRNAs that were previously implicated in cancer, including MEG3, ANRIL and UCA1, are deregulated by KSHV." (PMID 28715488, 2017). "Preliminary studies have shown the therapeutic potential of lncRNA UCA1 in cancer therapy, especially drug resistance." (PMID 28969100, 2017). "In cancer, the binding between UCA1 promoter core region and transcription factors or complex (C/EBPα, Ets-2, TAZ/YAP/TEAD and SMAD2/3) can enhance UCA1 promoter activity and gene expression." (PMID 28423704, 2017). "Some previously reported cancer-associated lncRNAs, such as HOTAIR, UCA1, and MALAT1, were found to be differentially expressed in our study, but none was in our top, validated list." (PMID 28415559, 2017). "Most studies have reported that lncRNA UCA1 is also specifically expressed in various cancer cells and involved in drug resistance." (PMID 28969100, 2017). "Numerous studies have demonstrated overexpression of UCA1 is an unfavorable prognostic indicator in cancer patients." (PMID 28423704, 2017). "In this review, we address the role of lncRNA UCA1 in anti-cancer drug resistance and discuss its potential in future clinical applications." (PMID 28969100, 2017). "Taken together, these studies confirm the pivotal role of lncRNA UCA1 in anti-cancer drug resistance to cisplatin, gemcitabine, 5-FU, tamoxifen, imatinib and EGFR-TKIs." (PMID 28969100, 2017). "Due to the vital effect of UCA1 on the cancer progress and CDDP resistance in OSCC, we intended to further investigate its molecular mechanisms." (PMID 29125238, 2017). "Long noncoding RNA UCA1 has emerged as a novel regulator in cancer initiation and progression of various cancers." (PMID 28569779, 2017). "Direct targeting of the UCA1 genomic locus is another method to knockdown UCA1 expression in malignant tumors." (PMID 28969100, 2017). "Here, we performed this meta-analysis to explore the correlation between high expression of UCA1 and clinicopathological characteristics and evaluate the prognosis role of UCA1 for cancer patients." (PMID 28423704, 2017). "Here we focused on functional significance of 1.4 kb isoform of UCA1 because of its most abundant distribution in various cancers." (PMID 28569779, 2017). "In cancers, UCA1 as an oncogene exhibited regulatory mechanisms responsible for cell proliferation, invasion, metastasis, apoptosis, metabolism and chemoresistance." (PMID 28423704, 2017). "The research conducted by Cheng and colleagues identified the role of UCA1 overexpression in cancer cells or small TKIs resistant cells." (PMID 28904641, 2017). "In recent years, increasing studies have reported that UCA1 was over-expressed in various cancers and UCA1 played important roles in the occurrence and development of human cancers." (PMID 28380443, 2017). "UCA1 overexpression promotes cancer progression by regulating different pathways, including PI3K, Wnt and mTOR-STAT3 signaling pathway." (PMID 27893417, 2017). "The meta-analysis indicated overexpression of UCA1 was significantly correlated with unexpected OS in patients with cancer (pooled HR = 1.85, 95% CI 1.62–2.10, p < 0.001)." (PMID 28423704, 2017). "The prognostic implication of UCA1 was also showed in the stratified analysis based on cancer type, histology type, sample size and cut-off value." (PMID 28380443, 2017). "Accumulating evidences indicated that UCA1 expression was up-regulated in various cancers, and high UCA1 expression was correlated with metastasis and prognosis." (PMID 27713161, 2017). "For the relationship between UCA1 and clinicopathological features in digestive system cancers, multiple studies have been performed on different kinds of the cancers." (PMID 28380443, 2017).
cancer (continued). "The prognostic value of lncRNA UCA1 in various human malignant tumors has been evaluated by many studies." (PMID 28969100, 2017). "UCA1 can also function as a competing endogenous RNA (ceRNA) in cancer cells by interacting with microRNAs (miRNAs), a type of regulatory ncRNA." (PMID 27046651, 2016). "UCA1, which was also called cancer upregulated drug resistant (CUDR), was originally identified in bladder transitional cell carcinoma in 2008 and suggested to promote cell proliferation and transformation." (PMID 28074092, 2016). "Recently, some studies have reported the relevance of UCA1 in cancer prognosis and the acquired resistance to drugs." (PMID 27329842, 2016). "Our meta-analysis provided evidence that high UCA1 expression was significantly correlated with a poor clinical prognosis in patients with various cancer types." (PMID 27517147, 2016). "Future studies should focus on the clinical utility of UCA1-based cancer diagnosis in clinical trials." (PMID 27329842, 2016). "With the treatment of tamoxifen, the size of tumors generated from MCF-7-R or T47D-R cells transfected with scramble control were greatly suppressed at each time point than those cancer cells transfected with si-UCA1." (PMID 27977766, 2016). "Numerous studies have shown that the expression of UCA1 was aberrantly upregulated in various cancer types." (PMID 27517147, 2016). "Among the 15 eligible articles, the OS according to UCA1 expression were reported in 13 articles (14 studies; 1,111 cancer patients)." (PMID 27517147, 2016). "The mechanism on regulatory activity of UCA1 in cancer invasion and metastasis has been explored in several cancer types." (PMID 27517147, 2016). "Several well-studied lncRNAs have been considered as potential targets or powerful predictors in cancers, such as Linc00668, H19 and UCA1." (PMID 27863388, 2016). "A growing number of studies have focused on the relationship between UCA1 and carcinoma, as well as interpreting its function in the progression of human cancer." (PMID 27517147, 2016). "We found that increased levels of UCA1 were significantly associated with shorter OS and PFS times in cancer patients." (PMID 27329842, 2016). "Therein indicating that, similarly to other cancer cells, UCA1 is able to promote proliferation of AML cells." (PMID 26053097, 2015). "LncRNA UCA1 has two isoforms: one is 1.4 kb in length; another isoform is 2.2 kb in length, which has also been identified by a different group as cancer upregulated drug resistant (CUDR)." (PMID 25760077, 2015). "In contrast, in cells that received a cancer causing stimulus, TBX3 and CAPERα physically separate: this activates production of UCA1 RNA and causes senescence." (PMID 24876127, 2014). "Moreover, urothelial cancer associated 1 (UCA1) and PRKCQ antisense RNA 1 (PRKCQ-AS1), were associated with proliferation, migration and apoptosis, especially in cancers." (PMID 38291538, 2024). "Considering all these results collectively, it appears that UCA1 exerts an oncogenic role in GC, as evidenced by the majority of studies illustrating its ability to promote cancer proliferation and metastasis, and inhibit apoptosis through interactions with multiple proteins, miRNAs, and genes." (PMID 38534790, 2024). "In the context of EGFR-TKI therapy, UCA1 may regulate signaling pathways that affect the sensitivity of cancer cells to the treatment." (PMID 39452836, 2024). "They found UCA1 to be upregulated in A431 and CAL-39 cells following their exposure to cancer-associated fibroblasts (CAF)-derived exosomes, and CAF-derived exosomal UCA1 mediated DDP resistance to both cell lines by sponging miR-103a and upregulating mitosis inhibitor protein kinase WEE1." (PMID 38534790, 2024). "UCA1 promotes malignant progression through various mechanisms in multiple cancers, including HNC." (PMID 36980216, 2023). "Multiple functions of UCA1 in cancer have been widely reported." (PMID 36829596, 2023).
cancer (continued). "The high expression of UCA1 in cancer tissues indicated a poor prognosis." (PMID 37564930, 2023). "UCA1 acts as an oncogenic lncRNA in several different cancers." (PMID 36639695, 2023). "In different cancer types, UCA1 may increase cell invasion by modulating Wnt/β-catenin and Notch signaling pathways, or by sponging specific miRNAs, such as miR-124, miR-126, or miR-143-3p." (PMID 36980216, 2023). "The expression level of UCA1 in cancer tissues was still controversial." (PMID 37564930, 2023). "However, our study cannot observe the difference in UCA1 expression between cancer and adjacent tissues." (PMID 37564930, 2023). "In patients with PSA <4 (who may be very low‐risk cancer patients), all cancer patients were identified with a PPV of 50% and an NPV of 100% by using UCA1 score ≥−0.475." (PMID 35289508, 2022). "Exosomal UCA1 secreted from hypoxic cancer cells reinforces cancer growth and angiogenesis in vivo." (PMID 35055115, 2022). "The lncRNA UCA1 has been widely studied in cancer samples and in trophoblast cells." (PMID 35740273, 2022). "This suggests the possibility that exosomal UCA1 is derived from cancer cells." (PMID 35055115, 2022). "This study demonstrated that UCA1 acts as a sponge for miR-204-5p, thus upregulating the expression of several target genes; UCA1 was found overexpressed in cetuximab-resistant cancer cells and their exosomes, in the progressive/stable disease group of patients." (PMID 35163397, 2022). "Similarly, at a cutoff value of UCA1 score ≥−3.47, all 91 cancer patients were diagnosed with a sensitivity of 1.0 and an NPV of 1.0." (PMID 35289508, 2022). "In addition, the pivotal role of UCA1 in the acquisition of resistance to anticancer drugs has been proven for several cancers." (PMID 34976187, 2022). "lncRNA UCA1 is often dysregulated in cancer and could act as an oncogene promoting cell proliferation and migration in many different types of human cancers." (PMID 33743811, 2021). "It has been reported that in some cancers, such as CRC, HCC, GC, adrenal cortical carcinoma and esophageal cancer, survival probability of patients is associated with UCA1 expression." (PMID 33777227, 2021). "INXS and UCA1 are lncRNAs that are up regulated and down regulated respectively in cancer cells." (PMID 35178359, 2021). "One of the reported cancer-related lncRNAs is urothelial carcinoma-associated 1 (UCA1) that was first discovered in 2006 as it was found to be overexpressed in bladder cancer (BC) cells, a cancer close to but not belonged to GI cancer." (PMID 33936199, 2021). "Interestingly, hypoxia which plays a central role in the development of PE is known to induce UCA1 expression through HIF1A in both cancer cell lines and primary cultures of STB." (PMID 34055770, 2021). "LncRNA UCA1 was upregulated in cancer tissues and inversely correlated with WT1-AS." (PMID 33514344, 2021). "Several studies also indicate that highly expressed UCA1 is related to poor clinicopathological features and may serve as a prognostic marker for cancer patients." (PMID 34760707, 2021). "Furthermore, up-frameshift protein 1, palmitic acid, cancer-associated fibroblasts and hepatitis B virus X protein can also regulate UCA1 expression and affect the proliferation of cancer cells, including HCC, GC and CRC cells." (PMID 33777227, 2021). "In PC and BC, UCA1 promotes the proliferation of cancer cells by inhibiting p27 expression." (PMID 33777227, 2021). "In other cancer types, UCA1 were also identified as targets of miR-1, miR-16, miR-18a, and miR-204." (PMID 34733326, 2021). "All these findings suggest an important role of UCA1 in the development of cancer." (PMID 33743811, 2021). "Transcription factors SATB1 and CAPERα/TBX3 downregulate UCA1 in cancers." (PMID 34733326, 2021). "UCA1 is a well-studied oncogenic lncRNA in many types of cancer including NSCLC." (PMID 33514344, 2021). "In the case of UCA1 high expression has previously been reported in different types of cancer." (PMID 34055770, 2021).